SLIRP-OT1 (SLIRP overlapping transcript 1)
Synonyms: C14orf178; FLJ25976
Gene: Long non-coding RNA gene on chromosome 14 (77,760,834 to 77,769,742, forward strand). Ensembl gene ENSG00000197734.
Diseases named in the same sentence as SLIRP-OT1 in open-access papers:
SLIRP-OT1 is named in the same sentence as 2 diseases in open-access papers, as found by Europe PMC text mining. Sharing a sentence is not in itself a finding about the gene and the disease.
SLIRP-OT1 shares sentences with these, for which no sentence is quoted: asthma (1 paper); cancer (1).